NR0B1 (nuclear receptor subfamily 0 group B member 1)
Diseases named in the same sentence as NR0B1 in open-access papers (continued):
Sharing a sentence is not in itself a finding about the gene and the disease.
hypogonadism (3 papers, 2012 to 2022). A disorder characterized by decreased function of the gonads. "Mutations in DAX-1/NR0B1 classically present in males during infancy or childhood with primary adrenal failure or less commonly isolated mineralocorticoid deficiency, with hypogonadism becoming apparent as failure to enter or progress through puberty." (PMID 28741070, 2017).
liver cancer (3 papers, 2020 to 2022). An epithelial or non-epithelial malignant neoplasm that arises from the liver. "Lin28b is a miR-125a target gene that, when downregulated, can inhibit liver cancer cell proliferation, NR0B1 (also called DAX-1) can inhibit the proliferation of liver cancer cells by suppressing the transcriptional activity of β-catenin." (PMID 33228611, 2020). "Six genes (BIRC5, CACYBP, NR0B1, RAET1E, SPINK5, SPP1) were up-regulated in the liver cancer tissues compared to the normal tissues in the TCGA HCC dataset, and S100A8 was downregulated." (PMID 33568167, 2021).
Parkinson disease (3 papers, 2021 to 2023). A progressive degenerative disorder of the central nervous system characterized by loss of dopamine producing neurons in the substantia nigra and the presence of Lewy bodies in the substantia nigra and locus coeruleus. "How are NEUROD1 and NR0B1 and NR0B2 impacted in Parkinson’s disease?" (PMID 34941945, 2021).
Hypoglycemia (2 papers, 2022 to 2025). A decreased concentration of glucose in the blood. "Hypoglycemia is not always present, as reported in a case study of a boy with a deletion of the entire NR0B1 gene." (PMID 40013223, 2025).
Kallmann syndrome (2 papers, 2012 to 2020). Kallmann syndrome (KS) is a developmental genetic disorder characterized by the association of congenital hypogonadotropic hypogonadism (CHH) due to gonadotropin-releasing hormone (GnRH) deficiency, and anosmia or hyposmia (with hypoplasia or aplasia of the olfactory bulbs). "After excluding mutations in KAL1 and NR0B1, which are associated with X-linked forms of CHH, genes associated with autosomal normosmic CHH or Kallmann syndrome were then screened." (PMID 22679506, 2012).
adrenocortical tumor (1 paper, 2021). "To this end, in order to further elucidate the influence of this NR0B1 variant on targeting genes, we preformed ChIP-sequence analysis of NR0B1 variants with an anti-NR0B1 polyclonal antibody in NCI-H295R human adrenocortical tumor cells." (PMID 34373561, 2021).
central precocious puberty (1 paper, 2023). "Furthermore, multiple patients with NR0B1 have been reported to experience central precocious puberty although the underlying mechanism remains to be elucidated." (PMID 37189438, 2023).
Granuloma (1 paper, 2021). A compact, organized collection of mature mononuclear phagocytes, which may be but is not necessarily accompanied by accessory features such as necrosis. "While granuloma formation is highly dependent on estrogen, NR0B1 is related to retinoic acid receptor, but data about its relation to periapical granuloma were not reported before." (PMID 34539639, 2021).
periapical granuloma (1 paper, 2021). Chronic nonsuppurative inflammation of periapical tissue resulting from irritation following pulp disease or endodontic treatment. "PPI revealed the relation between ESR1, ESRRA, and NR0B1 to periapical granuloma." (PMID 34539639, 2021). "MCODE-1 with the highest significance for nuclear receptor transcription pathway and the highest PPI in periapical granuloma was between RXRA, PPARG, ESR1, ESRRA, and NR0B1 proteins." (PMID 34539639, 2021).
sarcoma (1 paper, 2007). A usually aggressive malignant neoplasm of the soft tissue or bone. "However, we could not find out the GEO data that match to tumor genesis of the up-regulated NR0B1, though up-regulated NR0B1 gene was required for the transformed phenotype of certain sarcoma." (PMID 18034892, 2007).
tumor (42 papers, 2007 to 2026). "NR0B1 have been associated with the tumor phenotype mediated by EWS/FLI chimera in cell lines." (PMID 33924679, 2021). "For MMP10 and NR0B1, their positive expression was only shown in tumor tissues, especially in the metastatic lymph nodes and portal vein tumor thrombus, indicating their associations with HCC metastasis." (PMID 38374122, 2024). "For example, EWS-FLI1 stimulates the expression of c-Myc, Gli1 (Glioma-associated Oncogene Homolog 1) or NR0B1 (Nuclear Receptor subfamily 0 group B member 1), genes involved in tumor progression and metastatic development." (PMID 37752913, 2023). "We showed that the expression of nr0b1 in tumor tissue is strongly upregulated resembling the human phenotype." (PMID 35285802, 2022). "Higher expression of NR0B1 and IL20RA were associated with higher tumor histologic grade, and lower expression of ESRRG were associated with higher tumor histologic grade." (PMID 34868990, 2021). "A high expression of NR0B1 has shown high levels of tumor metastasis." (PMID 36699376, 2022). "(C) Relative mRNA expression of human EWSR1-FLI and zebrafish nr0b1 in normal and tumor tissues." (PMID 35285802, 2022). "In the present study, we identified five genes (LDHA, PPAT, BFSP1, NR0B1, and PFKFB4) associated with the tumour immune microenvironment in HCC patient cohorts that may be applied as potential biomarkers of HCC immunotherapy outcome." (PMID 33407546, 2021). "The results from these experiments are further supported by patterns of NR0B1 gene expression observed in tumor microarray data, wherein tumors harboring small GGAA microsatellites (<20 GGAA repeats) are those that have the lowest levels of NR0B1 gene expression." (PMID 25093581, 2014). "Similarly, metastases in lymph nodes and portal vein tumor thrombus also presented their significant expressional variation of PON1 and NR0B1 in the hepatocyte subclusters, which might be associated with their different invasion capacity." (PMID 38374122, 2024). "We found that CX3CR1+ macrophages enhanced the expression of the corresponding target tumor inhibitory genes, such as BTG2, EGR2, ERG3, NR0B1, and SDC4, on NR5A1+ tumor cells." (PMID 38658971, 2024). "The other tissues also presented expressional heterogeneities of the genes (normal livers: ADH4 and PON1; metastatic lymph nodes and portal vein tumor thrombus: PON1 and NR0B1) in their hepatocyte subclusters." (PMID 38374122, 2024). "Analysis of relative RNA expression showed upregulated expression of nr0b1 in tumor tissues compared to normal, correlating with EWSR1-FLI1 expression level in tumor samples (N of repeats = 3, N of replicas = 3)." (PMID 35285802, 2022). "In contrast, NR0B1 upregulation with positive correlation with microvascular invasion in HCC confirmed its positive expression in primary HCCs, metastatic lymph nodes, and portal vein tumor thrombus at single-cell level." (PMID 38374122, 2024). "Furthermore, we found that INHBA protein treatment up-regulated three tumor inhibitory genes, namely EGR2, ERG3, and NR0B1." (PMID 38658971, 2024). "In addition, immune infiltration assessment revealed that NR0B1 and FGF9 had potential to impact the tumor immune microenvironment." (PMID 35837663, 2022).
cancer (39 papers, 2007 to 2025). A tumor composed of atypical neoplastic, often pleomorphic cells that invade other tissues. "NR0B1, an atypical orphan nuclear receptor, was implicated in embryonic stem cells and cancer biology." (PMID 38374122, 2024). "Thus, NR0B1 is regarded as a typical X-linked cancer/germline gene (CG-X)." (PMID 27281610, 2016). "For MMP10 and NR0B1, their positive correlation or positive correlation trend with the anti-cancer drugs suggested HCC resistance to the drugs." (PMID 38374122, 2024). "Furthermore, transcription factors including SF1 (Steroidogenic Factor 1) and LRH-1 (Liver Receptor Homolog-1) have been reported to directly regulate NR0B1 expression in certain cancer types, adding further complexity to its regulation." (PMID 40864301, 2025). "Previous studies have shown that NR0B1 was associated with a variety of cancers, although its role in promoting or suppressing tumors is not consistent." (PMID 34966575, 2021). "The ectopic activation of NR0B1 is involved in the development of some cancers." (PMID 27281610, 2016). "We suggest that the up-regulations of the genes AKR1C1/C2, TM4SF1 and NR0B1 in SP of human adenocarcinoma A549 cells could be a target of poor prognosis in anti-cancer therapy." (PMID 18034892, 2007). "Therefore, enrichment of AKR1C1/C2, TM4SF1 and NR0B1 in SP of A549 cells might be a target of poor prognosis in cancer therapy." (PMID 18034892, 2007). "Augmented with the strong evidence from ImaGene, and as evidence by literature, investigating the role of NR0B1 in HNSCC and other cancer types further will be important." (PMID 36699376, 2022). "Thus, in ADCA, the activation of NR0B1 may promote the self-renewal of cancer cells." (PMID 27281610, 2016). "Moreover, it has been demonstrated that targeting the conserved cysteine (C274) residue of NR0B1 disrupts NR0B1 protein complexes, altering the transcriptional output and growth of NRF2-activated cancer cells." (PMID 40864301, 2025). "Additionally, they showed that targeting a conserved cysteine residue (C274) in NR0B1 disrupt NR0B1 complexes and impair the anchorage-independent growth of KEAP1-mutant cancer cells." (PMID 40864301, 2025). "Additionally, a higher level of H3K27me3 binding to the NR0B1 promoter was found only in non-cancerous tissues and cancer tissues with negative NR0B1 expression and not in cancer tissues with a strong NR0B1 signal." (PMID 27281610, 2016). "Considering a higher level of expression of NR0B1 observed in SP- than in MP-derived A549 cells, we propose that NR0B1 may be involved in the process of maintaining the “stem characters” of ADCA cells and promoting self-renewal in cancer cells." (PMID 27281610, 2016). "Furthermore, based on the level of NR0B1 expression in ADCA cells with different clinical stages, our results indicate that epigenetic modifications promote NR0B1 activation to maintain the self-renewal of cancer cells." (PMID 27281610, 2016).
genetic disorder (1 paper, 2016). "This genetic disorder is caused by mutations or deletions in NR0B1 gene located on the short arm of chromosome X. NR0B1 gene encodes for a nuclear receptor protein (DAX-1) which plays a key role in regulating the development of adrenal cortex, gonads, hypothalamus and pituitary gland." (PMID 27485500, 2016).
NR0B1 also shares sentences with these, for which no sentence is quoted: prostate carcinoma (17 papers); Obesity (8); IMAGe syndrome (5); infection (5); atherosclerosis (4); breast tumors (4); Insulin resistance (4); ovarian carcinoma (4); adrenoleukodystrophy (3); diabetes (3); dyslipidemia (3); enhanced S-cone syndrome (3); Hyperglycemia (3); male infertility (3); prostate tumors (3); retinal disease (3); rhabdomyosarcoma (3); 21-hydroxylase deficiency (2); adenocarcinoma (2); adenoma (2); alveolar rhabdomyosarcoma (2); autoimmune disease (2); bladder cancer (2); colon cancer (2); colorectal cancer (2); developmental delay (2); Duchenne muscular dystrophy (2); epilepsy (2); heart failure (2); Hyperinsulinemia (2).
A further 96 diseases each share a sentence with NR0B1 in 2 papers or fewer.